PLCXD2 (phosphatidylinositol specific phospholipase C X domain containing 2)
Description:
Catalyzes the hydrolysis of inositol from phosphatidylinositol (1,2-diacyl-sn-glycero-3-phospho-(1D-myo-inositol), PI). Could also hydrolyze various multi-phosphorylated derivatives of PI, such as phosphatidylinositol-4,5 bisphosphate (PIP2), releasing inositol-1,4,5-trisphosphate (IP3) and the protein kinase C activator diacylglycerol (DAG), therefore mediating cell signaling (Probable).
Synonyms: PLCXD-2; FLJ31579
Tractability: PROTAC: ubiquitination databases record sites on it.
Gene: Protein-coding gene on chromosome 3 (111,674,676 to 111,846,447, forward strand). Ensembl gene ENSG00000240891.
Subcellular location: Nucleus
Subcellular location (Human Protein Atlas): Nucleoplasm
Gene Ontology:
Molecular function: phosphoric diester hydrolase activity
Biological process: lipid metabolic process
Cellular component: nucleus
Genetic constraint (gnomAD): Loss-of-function variants: 21 observed, 30.35 expected, observed/expected ratio (o/e) 0.69, 90% interval 0.49 to 1. The upper end of that interval is the gene's LOEUF score, 1, which puts it in group 4 of 6, group 1 being the genes least tolerant of losing a copy. Missense variants: 369 observed, 394.36 expected, observed/expected ratio (o/e) 0.94, 90% interval 0.86 to 1.02. Synonymous variants: 140 observed, 160.5 expected, observed/expected ratio (o/e) 0.87, 90% interval 0.76 to 1.
Homologues: Orthologues: rat Plcxd2 (94% identical), guinea pig PLCXD2 (94% identical), pig PLCXD2 (94% identical), mouse Plcxd2 (94% identical), tropical clawed frog plcxd2 (67% identical), zebrafish plcxd2 (60% identical), Drosophila melanogaster CG10747 (31% identical), Caenorhabditis elegans F38E9.1 (28% identical). Paralogues in human: PLCXD3 (49% identical), PLCXD1 (31% identical).
Diseases named in the same sentence as PLCXD2 in open-access papers:
PLCXD2 is named in the same sentence as 4 diseases in open-access papers, as found by Europe PMC text mining. Sharing a sentence is not in itself a finding about the gene and the disease. The quoted sentences say what the papers report.
esophageal squamous cell carcinoma (1 paper, 2019). Esophageal squamous cell carcinoma (ESCC) is a type of esophageal carcinoma (EC) that can affect any part of the esophagus, but is usually located in the upper or middle third. "A recent GWAS has discovered three novel intronic single nucleotide polymorphisms in genes LRFN2 (rs2494938), DNAH11 (rs2285947) and PLCXD2 (rs2399395) that are associated with altered risk of esophageal squamous cell carcinoma (ESCC) among Han Chinese populations." (PMID 31053115, 2019).
gastric cancer (1 paper, 2022). A primary or metastatic malignant neoplasm involving the stomach. "For instance, lncRNA ACTA2-AS1 represses malignant phenotypes of gastric cancer cells by regulating miR-378a-3p/PLCXD2 axis." (PMID 36568518, 2022).
cancer (2 papers, 2021 to 2025). A tumor composed of atypical neoplastic, often pleomorphic cells that invade other tissues. "Among these upregulated genes, Dennd4a, Nfil3, Hspa1b, Chac1, Ddit4, Mex3b, Lysmd3, and Zbtb10 are mainly involved in oxidative stress and inflammation response, whereas Plcxd2, Dusp1, Cep85l, and Dusp8 are generally considered as tumor‐suppressor genes by inhibiting proliferation of cancer cells." (PMID 40231790, 2025). "The last one, PLCXD2, is a phospholipase located in the nucleus with no known connection to the placenta or pregnancy, but a novel intronic SNP has recently been associated with risk for several cancers." (PMID 34941772, 2021).
PLCXD2 also shares sentences with these, for which no sentence is quoted: tumor (1 paper).